MUC1 (mucin 1, cell surface associated)
Diseases named in the same sentence as MUC1 in open-access papers (continued):
Sharing a sentence is not in itself a finding about the gene and the disease.
tumor (continued). "Since TGF-β acts as a tumor promoter in high-MUC1 PDA cell lines and as a tumor suppressor in low-MUC1 PDA cell lines, it makes sense that neutralizing TGF-β in high-MUC1 cells (HPAFII), reduced tumor growth as the tumor promoting effect of TGF-β was inhibited by the antibody." (PMID 35237602, 2022). "Immunostaining for markers of perineurial cells such as claudin-1, mucin-1 (MUC1, also known as epithelial membrane antigen [EMA]), and glucose transporter protein-1 (GLUT-1) is also commonly used in the identification of peripheral nerves as well as neoplasms originating from perineurium." (PMID 36230740, 2022). "Additionally, EGFR, Mucin-1 (MUC1), and integrin beta-4 (ITGB4), which promote tumor growth and metastasis, are poor prognostic factors for this tumor." (PMID 36407096, 2022). "Additionally, through the analysis of exosomes, more and more tumor-related biomarkers have been found, such as HER2, EpCAM, MUC1, CA125, and so on." (PMID 36235208, 2022). "An aberrantly glycosylated tumor form of MUC1 (tMUC1) has been found overexpressed in greater than 95% of all TNBC, while no significant tMUC1 expression is detected on normal breast tissues, suggesting a tumor-specific antigen target in TNBC treatment." (PMID 35795050, 2022). "We show that endocytosis inhibitors augment the availability of MUC1-Tn/STn epitopes on tumor cells but do not further enhance ADCC in NK cells." (PMID 34070311, 2021). "The present study showed that combination of EpCAM/CD3 BsAb and MUC-1/CD3 BsAb could dramatically enhance elicited CTL response, as well as promote cytokine production in tumor cell lines and primary tumor cells." (PMID 34522164, 2021). "Recent findings demonstrate that under hypoxic conditions, MUC1 elevates expression of proangiogenic gene levels such as CTGF, PDGF-B, and VEGF-A that, in turn, promotes the synthesis of new blood vessels within the tumor and tube formation within ECs." (PMID 33836774, 2021). "Moreover, previous reports indicated that MUC1, COPS6, HOTAIR, COL6A1 were served as biomarkers for PAAD and had tumor-suppressive or tumor-promoting ability." (PMID 34285140, 2021). "In addition, MUC1-CPD-L1 signalling promoted activation of CD8C T cells, demonstrating that MUC1-C is a potential target for reprogramming the tumor microenvironment." (PMID 34207342, 2021). "Tumor-associated cfRNA (e.g., CEACAM6, MUC1) was present in NSCLC LM patients’ CSF, but not in controls (CEACAM6 detection sensitivity 88.24% and specificity 100%)." (PMID 34625644, 2021). "Addition of endocytosis inhibitors to tumor cells in the presence of humanized anti-MUC1 antibodies had no negative effect on tumor cell viability." (PMID 34070311, 2021). "When MUC1-negative tumour cells (A431)were used as the stimulator, MUC1-specific CAR-T cellsshowed no significant secretion of IL-2 (30 ± 2.82 pg/mL, 1-fold), TNF alpha (8 ± 2.82 pg/mL, 1.7-fold) and IFN-γ (22 ± 2.82 pg/mL, 1.2-fold)." (PMID 32347044, 2021). "Furthermore, our data also showed that knockdown of MUC1 expression could significantly suppressed tumor cell proliferation, invasion, migration, and cell cycle progression in vitro, and could significantly inhibit tumor growth in mouse subcutaneous xenograft model." (PMID 34729096, 2021). "Immunohistochemical data showed that MUC1 was rated as strong or moderate expression in 59.3% (127/214) of tumor tissues and 22.9% (49/214) in the corresponding adjacent normal intrahepatic bile duct tissue." (PMID 34729096, 2021). "Previously, we have published the differences in the MDSC function in a MUC1-positive versus negative tumor and the downstream effects on anti-tumor immunity." (PMID 34070449, 2021). "In the meantime, the use of a panel of tumor models of NCI-H295R, SJ-ACC3, and MUC-1 xenograft models could help the clinical translation of therapeutic regimens in the future." (PMID 34567112, 2021).
tumor (continued). "The complex was able to carry DOX into MUC1 positive tumor cells but lowered the toxicity to MUC1 negative cells." (PMID 33883615, 2021). "Once tumours were palpable, mice were injected with VLPs delivering either survivin, MUC1, both, or no antigen (n = 10 mice/group)." (PMID 34066318, 2021). "Although direct binding to the Tn antigen has not been observed for most MUC1 antibodies generated in the efforts to develop anti-tumor therapeutics, Tn glycans appear to play a role in antigen binding." (PMID 34640530, 2021). "While MUC1 has been ranked as the highest priority cell-surface cancer antigen, CAR T cell targeting of ErbB dimers has demonstrated great potency, but limited tumor specificity." (PMID 35028604, 2021). "These antigens are overexpressed by tumor cells but also shared with normal tissue (eg, carcinoembryonic antigen (CEA), epithelial cell adhesion molecule (Ep-CAM), mucin-1 (MUC-1), melanoma antigen recognized by T cells-1 (MART-1/Melan-A), glycoprotein 100 (gp100), and tyrosinase (Tyr))." (PMID 33268350, 2020). "The results showed that the vaccine significantly reduced the proportion of MDSCs in both the spleen and the TME, and significantly increased the CD8/MDSC ratio, suggesting that the recombinant MUC1-MBP vaccine reversed immunosuppression by reducing MDSCs and thus controlled tumor growth." (PMID 32823603, 2020). "Although most mAbs recognize MUC1 irrespective of its glycosylation pattern, several targeting moieties target a highly tumor-specific conformational MUC1 epitope induced through increased expression of truncated O-glycans sTn and Tn." (PMID 33371487, 2020). "The expression of MUC1 was significantly lower in non-cardia and cardia tumor tissues than that in normal tissues." (PMID 32122390, 2020). "In contrast, there was little difference in CIPp-MUC1 tumor volume with or without disulfiram treatment." (PMID 33375426, 2020). "Autologous tumor lysate or peptide antigens (WT1, MUC1, CEA) according to the HLA-A pattern." (PMID 33679709, 2020). "Among the best-known membrane-bound mucins, MUC1 and MUC4 have been extensively proposed as drivers of pancreatic carcinogenesis because they promote tumor growth, proliferation, oncogenic signaling, cell metabolism, epithelial–mesenchymal transition (EMT), and metastasis." (PMID 33182511, 2020). "The highest MUC1 expression was achieved 72 hours after IL22 cytokine addition, all the cytotoxic experiments were performed at the 72nd hour to detect the apoptosis of tumor cells." (PMID 31800160, 2020). "This CAR-T cell therapy uses the MNC2 antibody, which recognizes an epitope on MUC1* that is revealed when MUC1 is cleaved on tumor cells but not on healthy cells." (PMID 32560392, 2020). "The clinical parameters including age, gender, tumor subtype, T value, N value, tumor stage and grade are not significantly correlated with IL-17RB, MUC1, or MUC4 expression." (PMID 33082357, 2020). "IHC for MUC1 and SOX17 on both tumor and normal organoids has confirmed their glandular origin." (PMID 32552764, 2020). "The expression of MUC1 in non-cardia tumor tissue was significantly lower than that in paired adjacent normal tissues (P = 9.87 × 10− 10)." (PMID 32122390, 2020). "It is mainly because IL22 could induce the expression of MUC1, allowing CAR‐T cells to bind more accurately to tumor cells." (PMID 31800160, 2020). "The combination of AR20.5, anti-PD-L1 antibody and PolyICLC rejected human MUC1 expressing tumors and provided a long-lasting, MUC1-specific cellular immune response, which when adoptively transferred to human MUC1 transgenic (MUC.Tg) mice, provided protection against tumor formation." (PMID 33167508, 2020). "We and others previously reported that antibodies specific to tumor MUC1 preferentially bind to the tumor cell surface, but not healthy cells." (PMID 33084221, 2020).
tumor (continued). "It is well known that within the hypoxic tumor niche, a high level of HIF-driven adaptations is observed in terms of ECM modeling, expression of immune surface markers PD-L1, MUC-1, CD73 and hypoxia-induced extracellular vesicles." (PMID 33015012, 2020). "More importantly, blocking STn-MUC1 and CD44 glycoforms partially reverted DC maturation, suggesting that targeting STn-expressing glycoproteins may allow circumventing tumor-induced tolerogenic mechanisms." (PMID 31157165, 2019). "BBiApt was found to bind with the extracellular domains of membrane proteins of MUC1- or CD16-positive cells, and could recruit more CD16-positive immunocytes around the MUC1-positive tumor cells." (PMID 30699986, 2019). "A 1.3- and 1.9-fold decrease in HER-2 (3%; p < 0.05) and MUC-1 (11%) antigen recognition was observed by the TCRs of the CD8 + T cells primed with DCs matured in the absence of tumour-specific lysate, respectively." (PMID 30283982, 2019). "In addition, Muc1 was downregulated, while Fn1 and Itga5 were upregulated in PDC compared to classical tumours." (PMID 31439856, 2019). "Altogether, these data indicate that SPN and MUC1 modulate tumor cell sensitivity to CD20xCD3 bsAb independent of CD20 expression, while increased expression of CD52 directly affects CD20 cell surface levels." (PMID 31882897, 2019). "Because pro-inflammatory cytokines have been previously shown to stimulate expression of membrane-bound mucins such as MUC1, MUC4, and MUC16 in tumor cells, we hypothesized that ascites could enhance MUC16 expression in HPMCs." (PMID 31039761, 2019). "MUC2 expression was more frequently found in N-cadherin-negative CCs, while the expression of MUC1 was similar in both groups of tumours." (PMID 30875782, 2019). "Additionally, it was shown that the MUC1 SEA domain originates from heparin sulphate proteoglycan of basement membrane (HSPG2; perlecan), an inducer of tumour cell growth." (PMID 30875782, 2019). "It was reported that MUC5A, MUC2, CK20, c-erbB2 were completely positively expressed in tumor cells of UCGD, meanwhile, MUC1, CK7, 34βE12 could also be the markers helping distinguishing similar cells." (PMID 30926888, 2019). "Notably, HPK1 KD mice showed markedly increased pro-inflammatory pathways in response to priming with tumor antigens as shown by the enhanced related gene expression, e.g. S100A8, GZMB, NKp44, CXCL14, CX3CL1, CD1d2, KLRG1, CD11c, NLRP3 and MUC1." (PMID 30913212, 2019). "On the other hand, it was reported that binding of the soluble form of Siglec-9 to the MUC1 induced recruitment of β-catenin and subsequent cell growth in vitro rather than suppression of the tumor growth, which results disagreed with our ones in vivo." (PMID 29342882, 2018). "Here, the MUC1 positive tumor demonstrated uptake of the aptamer-functionalized nanoparticles, while the MUC1 negative tumor did not uptake the nanoparticles, which allowed for detection of the MUC1 signal with SERS upon ex vivo analysis." (PMID 29751641, 2018). "To explore the mechanism of failure, we examined both the tumor and 1G.4/7ICR T cells before and after treatment and saw no change in either MUC1 antigen expression on malignant cells or CAR expression by the T cells." (PMID 29747685, 2018). "However, given the role of MUC1 and IL4 in tumor progression and metastasis, it is highly unlikely that the tumor will downregulate either one or both of these molecules." (PMID 29747685, 2018). "The anti-hMUC1 monoclonal antibody effectively targeted tumor-specific MUC1 without affecting normal tissue." (PMID 29987260, 2018). "It is also interestingly that binding of tumor-produced MUC1 to Siglec-9 induces negative immunomodulation." (PMID 29342882, 2018).
tumor (continued). "The MA3-Dox complex showed specific binding and cellular uptake of Dox with significant cytotoxicity in MUC1-positive tumor cells, but not in MUC1-negative cells." (PMID 29617327, 2018). "Additionally, survivin, MUC-1, CEA, erbB2 and CA19-9 antigens were also detected in a significant number of tumor samples from GBC patients, suggesting that these were suitable antigen targets for immunotherapy approaches." (PMID 29600445, 2018). "For Muc1 positive tumor cells, HT29, LS174T, or SKOV3, Muc1-Bi-1 alone had no cell killing activity at 1 μg/ml or 10 μg/ml." (PMID 29357376, 2018). "We found that the production of both anti-PANC-1 and anti-MUC1 Abs was effectively elicited by vaccination with α-gal(+) PDAC tumor lysates from patients treated with or without NACRT." (PMID 29077749, 2017). "Also, the availability of patient DNA from the non tumoral tissue highlighted that the SNVs identified in the tumor tissue and Chor-IN-1 cell line were mainly germline, with four exceptions involving TECTA, SART3, KEL and MUC1 genes." (PMID 28835717, 2017). "In 4 out of 8 mice, the primary Renca-MUC1 tumor regressed on the right flank and no growth of the challenged tumor on the left flank was observed upon follow up for up to 70 days, when mice were killed for IFN-γ assay." (PMID 28116088, 2017). "Of note were that these effects were only evident in HeLa229/shCTL tumor but not in HeLa229/shMUC1 tumor, supporting a MUC1 dependency." (PMID 28796259, 2017). "In pilot experiments, titration experiments using radiation doses of 5 and 8 Gy and MVA-MUC1-IL-2 vaccine doses of 105, 106 and 107 PFU showed that the combination of 8 Gy tumor irradiation with 107 PFU MVA-MUC1-IL-2 was the most effective for the treatment of Renca-MUC1 s.c. tumors." (PMID 28116088, 2017). "We were surprised to see low or no internalization of our antibodies after binding MUC1 on the tumor cell surface." (PMID 27545199, 2016). "Some of the approved included; Cancer antigen 15-3 (CA 15-3) and Cancer antigen 27.29 (CA 27.29) kits that measure Mucin 1 (MUC1) levels in peripheral blood, assessment of carcino-embryonic antigen (CEA) levels in blood and ER, PgR, HER2 status of the primary tumour." (PMID 27189371, 2016). "Even though peptide-sensitized T-cells often recognized tumor digests robustly in vitro, tumor protection was never observed against B16.MUC1 challenges in vivo." (PMID 26788922, 2016). "WT or MUC1.Tg mice were immunized three or four times with either peptides or rotating lysates and then challenged with MUC1-expressing tumor cells (B16.MUC1) that were not part of prior cell lysate immunizations." (PMID 26788922, 2016). "Inoculation of B16.MUC1 with either naive T-cells or lysate-immunized MUC1-specific T-cells did not prevent tumor growth." (PMID 26788922, 2016). "Mice vaccinated to peptide prior to B16.MUC1 challenge displayed rapid tumor progression indistinguishable from unvaccinated mice, but, surprisingly, also displayed down regulated MUC1 and MHC expression." (PMID 26788922, 2016). "Some tumor models such as B16.MUC1 and MC38.MUC1 have proven to be preventable by MUC1 vaccines." (PMID 26788922, 2016). "Synthetic Tn antigen-containing MUC1 glycopeptides, representing the tumor-associated MUC1, are processed to smaller fragments for loading into the MHC class II molecule without removing the glycans attached to the original MUC1 peptide." (PMID 27153100, 2016). "Underscoring that tumor control was a function of MUC1 recognition, rotating lysate-immunized mice were not protected against B16.neo." (PMID 26788922, 2016). "CD62Llow effector T-cell subsets were stimulated in vitro for 1–2 weeks with DCs pulsed with the immunizing peptides or, for the group immunized with rotating tumor cell lysates, with B16.MUC1 tumor lysate not used during previous in vivo priming." (PMID 26788922, 2016).
tumor (continued). "The objective of this study was to improve the design of a MUC1 vaccine for HLA-A*0201 individuals, relying on heteroclitic optimizations of potential anchor amino acids with and without tumor-specific glycosylation of the peptides." (PMID 27367740, 2016). "We next screened by flow cytometry this panel of cell tumour phenotypes with epithelial markers (EpCAM, E-cadherin, Muc1, claudin-3 andclaudin-4) or non-epithelial markers (N-cadherin, vimentin, CD66, EGFR, FGFR, EphB4,ALDH1 and CD49f)." (PMID 27711186, 2016). "Two patients from the low MUC1 expression group had recurrences of the tumor within the follow-up period, whereas none of the patients in the group with high MUC1 expression did, although the difference was not statistically significant (p = 0.14)." (PMID 27846863, 2016). "As demonstrated here, a diversity of cytokines induce MUC1-ARF expression, suggesting that a specific milieu of cytokines and growth factors present in the tumor microenvironment may govern its restricted expression." (PMID 27768738, 2016). "These antibodies bind hypoglycosylated MUC1 on human cancer cell lines and tumor tissues but show no reactivity against fully-glycosylated MUC1 on normal cells and tissues." (PMID 27545199, 2016). "MUC1 is the most attractive TAA, a status that is attributable not only to its dramatic alterations in cancer but also to the prevalence of these changes across multiple tumor types." (PMID 27825118, 2016). "It was, therefore, evident that every tested MUC1 vaccine composition exerted a strong selection pressure, even when tumor progression rather than cure was observed." (PMID 26788922, 2016). "We detected a significant increase in expression of both MUC1 and CIN85 associated with advanced tumor stage and lymph node metastasis." (PMID 25675408, 2015). "However, treatment of cells with the combination of mL4-3 and L1-7(N) modulated tumor-cell phenotype, increasing the surface expression (either percentage or MFI) of CEA, MUC-1, ICAM-1, Fas, Trail-R1, Trail-R2, and calreticulin." (PMID 26579226, 2015). "Furthermore, mice immunised with either AntpMUC1Kb or TATMUC1Kb peptides generated strong MUC1-specific IFN-γ responses and inhibited the growth of B16-MUC1 tumours." (PMID 26247926, 2015). "MUC1 can mediate production of several growth factors such as connective tissue growth factor (CTGF), platelet-derived growth factor A (PDGF-A) and PDGF-B, which promote the proliferation and survival of tumor cells." (PMID 26367866, 2015). "Li and coworkers used vaccines containing full-length MUC1 VNTR epitopes glycosylated variably at a Ser and/or Thr residue within the VNTR (HGVTSAPDT*RPAPGS*TAPPA) to induce IgG antibodies capable of recognizing tumor cells." (PMID 26557640, 2015). "The cut-off value of MUC1 positive or negative was mostly estimated by the proportion or area of positive stained cell in tumor tissue that ranged from 0 to 35%, while 4 studies did not reported the exact definition of MUC1 positive." (PMID 26367866, 2015). "Anti-MUC1 IgG level in NAF was higher in triple negative tumors (P = 0.02); serum anti-MUC1 IgG levels were significantly higher in patients with ER (−) tumor and recurrent disease (P = 0.01); NAF anti-MUC1 IgA levels were significantly higher in patients with LVI and Her2-neu (+) tumors (P < 0.05)." (PMID 26693201, 2015). "The expression of MUC1 in CRC tissue can be determined by IHC method with monoclonal antibody against MUC1, which can be done simultaneously when pathologists conduct pathological diagnosis with tumor tissue obtained from surgery or biopsy." (PMID 26367866, 2015).